TIGIT (T cell immunoreceptor with Ig and ITIM domains)
Diseases named in the same sentence as TIGIT in open-access papers (continued):
Sharing a sentence is not in itself a finding about the gene and the disease.
colorectal cancer (55 papers, 2015 to 2026). A primary or metastatic malignant neoplasm that affects the colon or rectum. "Intratumoral bacteria like Fusobacterium nucleatum, a bacterium linked to colorectal cancer, can suppress anti-tumor immunity by binding to TIGIT via its Fap-2 protein, thereby blocking tumor cell elimination." (PMID 41246357, 2025). "Fibroblast activation protein 2 (Fap2), which directly interacts with TIGIT in human NK and T cells to cause immunosuppression, has been discovered to be secreted by Fusobacterium nucleatum, a bacterium linked to colorectal cancer." (PMID 38229100, 2024). "Among these immune checkpoint genes, highly expressed CTLA4, LAG3 and TIGIT has been treated as diagnostic biomarkers for colorectal cancer." (PMID 37693891, 2023). "Overall, TIGIT+ cells in colorectal cancer were linked to advanced disease, early recurrence, and lower survival rates." (PMID 35656508, 2022). "When looking at survival data in patients with breast or colorectal cancer, TIGIT expression in the tumors was linked to improved OAS." (PMID 36551992, 2022). "TIGIT expression was found to be strongly associated with poor prognosis in colorectal cancer and positively correlated with pathological stages in renal clear cell carcinoma, kidney renal papillary cell carcinoma, and uveal melanoma." (PMID 35656508, 2022). "In colorectal cancer research, it has also been reported that cancer-associated fibroblasts (CAFs) can directly suppress effector T cell function, impair proliferation, and promote exhaustion through the TIGIT–NECTIN2 axis, thereby driving immunosuppression." (PMID 41031085, 2025). "Concerning a microbiota-mediated immune regulation, a previous study could show that Fusobacterium nucleatum, a commensal bacterium in the tumor microenvironment associated with colorectal cancer, can directly bind TIGIT leading to suppression of antitumor NK-cell and T-cell response." (PMID 38017389, 2023). "Remarkably, the promoter methylation status of LAG3, TIGIT, and PD-L1 was anti-correlated with gene expression in colorectal cancer." (PMID 39064019, 2024). "In ex vivo experiments, combination treatment including atezolizumab (anti-PD-L1 mAb) and tiragolumab (anti-TIGIT mAb) restored the functionality of TILs from colorectal cancer patients." (PMID 37670328, 2023). "Anti-TIGIT mAbs alone or in combination with anti-PD-L1 mAbs synergistically exerted their effects in a CT26 colorectal cancer model mice." (PMID 37670328, 2023). "In patients with colorectal cancer, high TIGIT expression correlated with T cell exhaustion, advanced disease, early recurrence, and poor survival." (PMID 37291608, 2023). "By secreting TGF-β1, colorectal cancer cells can up-regulate TIGIT expression, promote CD8T cell depletion and facilitate tumor immune escape." (PMID 35911673, 2022). "It has shown that the expression of PD-1 and TIGIT is elevated in colorectal cancers that are defective in mismatch repair." (PMID 35433470, 2022). "Preclinical studies in a murine model of colorectal cancer showed that the dual blockade of PD-1/PD-L1 and TIGIT led to remission in the whole studied group vs. the regression of the tumors with the blockade of a single pathway." (PMID 36497240, 2022). "Tumor-intrinsic expression of TIGIT has been reported in patients with colorectal cancer, and was shown to promote tumor progression by competing with CD226 in binding to CD155." (PMID 36163179, 2022). "The double blocking of the TIGIT and PD-1/PD-L1 pathway showed synergistic antitumor effects in colorectal cancer and ovary cancer by upregulating the effector activity of T cells and NK cells." (PMID 36613817, 2022). "It has now been demonstrated that TIGIT is up-regulated in colorectal cancer with infiltrating lymphocytes, including CD3, CD4, CD8, and NK cells." (PMID 35911673, 2022).
colorectal cancer (continued). "Although TIGIT has been identified on the surface of colorectal cancer cells a role for TIGIT in promoting cancer cell survival via tumour cell intrinsic signalling has not been identified in previous studies." (PMID 35245832, 2022). "The density of CD8+T cells in the tumor margin increased, and expression of PD-1 and TIGIT was up-regulated, compared with that in the tumor center of colorectal cancer." (PMID 35433470, 2022). "We found that the proportion of CD3+TIGIT+ T cells was increased in peripheral blood and cancer tissue in colorectal cancer patients when compared with the healthy donors." (PMID 34659197, 2021). "In this study, we found that the expression of TIGIT was upregulated on the T cell surface in colorectal cancer patients and had exhibited a significant relationship with clinical prognosis." (PMID 34659197, 2021). "TIGIT negatively regulates the human immune function, promotes the proliferation and escape of tumor cells, and accelerates the progression of colorectal cancer." (PMID 34659197, 2021). "The results suggested that the percentage of CD3+TIGIT+ T cells(32.50 ± 8.74) in peripheral blood of colorectal cancer patients was significantly increased compared with that of HDs (22.28 ± 7.16)(P<0.01)." (PMID 34659197, 2021). "Taken together, these findings demonstrated that TIGIT overexpressed T cells had impaired glucose uptake and metabolism in colorectal cancer patients." (PMID 34659197, 2021). "In the current study, we found that the percentage of CD3+TIGIT+T cells was significantly increased in the peripheral blood and tumor tissues of patients with colorectal carcinoma." (PMID 34659197, 2021). "Double fluorescence staining revealed a higher degree of CD3+TIGIT+ T cell infiltration in colorectal carcinoma tissues than adjacent normal tissues, which was supported by the quantitative analysis." (PMID 34659197, 2021). "The infiltration of CD3+TIGIT+ T cells was further examined in cohort 2 of 90 matched sets of colorectal carcinoma tissues and adjacent normal tissues using tumor tissue microarray analysis." (PMID 34659197, 2021). "Our previous study revealed the expression of TIGIT on colorectal tumor cells and its pivotal role in colorectal cancers." (PMID 32894141, 2020). "In colorectal cancers, expression of TIGIT and PD-1 was considerably higher in T cells located at the invasive margin as compared to T cells in the tumour centre." (PMID 30733837, 2019). "Although TIGIT expression occurs mostly on CD45+ immune cells in human colorectal cancer, the obvious expression of TIGIT was observed on CD45− cells in some cases." (PMID 30555485, 2018). "In the current study, we found that TIGIT was overexpressed in tumor tissues and expressed higher than PD-1 in most of the colorectal cancer samples." (PMID 30555485, 2018). "Monoclonal antibody-mediated blockade of TIGIT or combined blockade of TIGIT and PD-L1 boosted the antitumor activity of NK cells in mouse models of colorectal cancer and efficiently delayed tumor growth." (PMID 30463262, 2018). "Unexpectedly, we firstly discovered that TIGIT was expressed in mRNA level in murine colorectal cancer cell lines CT26 and MC38." (PMID 30555485, 2018). "To investigate the potential role of TIGIT in tumor cells, we established stable TIGIT knockout (KO) colorectal cancer cell lines using CRISPR/Cas9 system." (PMID 30555485, 2018). "The reason for the expression difference is still unclear, and the expression of TIGIT on colorectal cancers after certain treatments or on other cancer types remains to be investigated." (PMID 30555485, 2018). "TIGIT and its ligand CD155 (PVR) are emerging immune checkpoints in colorectal cancer (CRC), but their associations with mutational subtypes and the tumor immune milieu remain unclear." (PMID 41596586, 2026). "Moreover, PD-1 KO together with LAG-3, TIM-3, TIGIT, and TGFbR2 KO showed improved anti-tumor activity and survival compared to PD-1 alone on a colorectal cancer model." (PMID 41354926, 2025).
colorectal cancer (continued). "Furthermore, F. nucleatum Fap2 binds to Gal-GalNAc of colorectal cancer, engages TIGIT (an inhibitory immune receptor) on NK and T cells, and protects tumors from host immunity attack." (PMID 38302656, 2024). "The efficacy of targeting the TIGIT/CD155 signal axis may depend on further genotyping in colorectal cancer." (PMID 35433470, 2022). "In human colorectal cancer, it has been proposed that concomitantly targeting PD-L1 and TIGIT could restore intratumoral CD8+ T cell function." (PMID 36544779, 2022). "Altogether, our findings support the development of colorectal cancer immunotherapies targeting TIGIT, which could be used in combination immune checkpoint therapy in colorectal cancer." (PMID 36077799, 2022). "TIGIT blockade alone or in combination with PD-1 may be a potential strategy for treating colorectal cancer." (PMID 34659197, 2021). "We then investigated whether these TIGIT overexpressed CD3+T cells had altered cell function in colorectal cancer patients." (PMID 34659197, 2021). "TIGIT antibody can restore the T cells effectors function and metabolic activity, which may be a potential treatment for colorectal cancer." (PMID 34659197, 2021). "TIGIT plays an important role in the pathogenesis of various tumors, but its immune escape in colorectal cancer remains unclear." (PMID 34659197, 2021). "Furthermore, TIGIT blockage also increased apoptosis and changed the cell cycle distribution of colorectal cancer cells." (PMID 34659197, 2021). "However, expression of TIGIT extended to other stromal infiltrating cells, whereas PD-L2 was also expressed by colorectal cancer cells." (PMID 34975867, 2021). "Our results suggest that blocking TIGIT and restoring T cell metabolic activity may represent a possible approach to immunotherapy against colorectal cancer." (PMID 34659197, 2021). "Our study illustrates the specific mechanism of TIGIT in immunotherapy of colorectal cancer." (PMID 34659197, 2021). "Despite these findings, it remains largely unknown about how TIGIT modulates the tumor microenvironment, and also whether it is a promising therapeutic target in colorectal cancer." (PMID 30555485, 2018). "Further, our results demonstrated that tumor-intrinsic TIGIT could maintain tumor growth in colorectal cancer models." (PMID 30555485, 2018). "Taken together, these results indicated that tumor-intrinsic TIGIT contributed to helping tumor growth in murine colorectal cancer models, and this effect might depend on the host immune response." (PMID 30555485, 2018). "To study whether TIGIT could serve as a potential target in colorectal cancer, we analyzed the expression of TIGIT in colorectal cancer patients of Musella's cohort (GSE37182)." (PMID 30555485, 2018). "Furthermore, TIGIT was significantly hypomethylated in colorectal cancer." (PMID 39064019, 2024). "Similarly, T cell dysfunction in colorectal cancer has been related to diminished glucose metabolism since TIGIT expression, and metabolic alterations induced by colorectal cancer cells are restored by antibody-mediated TIGIT blockade." (PMID 36713558, 2022). "Furthermore, high TIGIT expression was linked to advanced disease, early recurrence, and lower survival rates, and with advanced TNM stage and better disease-free survival (DFS) in colorectal cancer patients with mismatch repair deficiency." (PMID 35656508, 2022). "For example, in colorectal cancer, DNA hypomethylation and two repressive histone marks, H3K9me3 and H3K27me3, were shown to be involved in the upregulation of CTLA-4 and TIGIT genes." (PMID 39064019, 2024). "TIGIT was highly expressed on CD4+ T cells and CD8+ T cells in all three tumors, moderately expressed on NK cells in colorectal cancer, and moderately expressed in monocytes in lung cancer." (PMID 39120585, 2024).
colorectal cancer (continued). "Moreover, ILC1-like cells from colorectal cancer patients that are absent in normal mucosa are enriched in genes encoding for inhibitory receptors including TIGIT and TIGIT+ ILC1-like cells were identified by flow cytometry within tumors but not normal tissues." (PMID 38567059, 2023). "Our results highlight the strong expression of TIGIT and its ligand, CD155, in tumors, suggesting the role of the TIGIT/CD155 axis in colorectal cancer." (PMID 36077799, 2022). "Previous studies have demonstrated that TIGIT and CD155 were elevated in colorectal cancer compared with normal tissue." (PMID 35433470, 2022). "Our results were consistent with a recent study demonstrating that TIGIT expression was inversely correlated with the expression of cytotoxic cytokines, including IFNγ, from CD8+ T cells infiltrating colorectal cancer." (PMID 35053427, 2022). "Thus, TIGIT may serve as an immunotherapy target for colorectal cancer." (PMID 35433470, 2022). "Another study discovered a higher TIGIT+CD3+ T cell subpopulation in the peripheral blood and cancer tissue of colorectal cancer patients than in healthy donors." (PMID 35656508, 2022). "A TIGIT/CD226 dysbalance with high TIGIT and low CD226 expression on intra-tumoral NK cells been shown in multiple human tumors, e.g. colorectal cancer (CRC), ovarian cancer and HCC, and compromises intra-tumoral NK cell functions." (PMID 34367161, 2021). "We next examined TIGIT and PD-1 expression in fresh tumor samples from patients with colorectal cancer, and noticed that TIGIT was highly expressed on CD45+ cells in colorectal cancer samples (tumor vs. peri-tumor, p < 0.01)." (PMID 30555485, 2018). "Therefore, TIGIT could be a potential target for immunotherapy of colorectal cancer." (PMID 30555485, 2018). "In summary, ARG1 was positively correlated with TIM3, TIGIT and ICOS in colorectal cancer." (PMID 38012650, 2023). "According to this data, GSEA computational analysis revealed that TIGIT expression in colorectal cancer drives the negative regulation of cytokine-cytokine receptor interaction pathway, chemokine signaling, and cytotoxic function of NK cells." (PMID 35656508, 2022). "As a classic non-steroidal anti-inflammatory drug, Aspirin inhibits colorectal cancer cell proliferation and induces tumor cell apoptosis through TIGIT/CD155 signaling axis." (PMID 35433470, 2022). "CD3+TIGIT+T and CD3+TIGIT-T cells were sorted from colorectal cancer patients’ PBMCs." (PMID 34659197, 2021). "We have also shown that antibody blockade of TIGIT could restore CD3+ T cell activity and inhibit tumor growth, which might suggest a promising target for colorectal cancer." (PMID 34659197, 2021). "Combination strategies—for example, dual TIGIT/PD-1 blockade or STING agonists plus PD-1 inhibitors—have generated higher response rates in select PD-L1–high and MSI-high cohorts but also highlight tumor-intrinsic resistance mechanisms in “cold” microsatellite-stable colorectal cancers." (PMID 40777027, 2025). "In d-MMR colorectal cancer, which is the archetypal example of an inflamed TME, there was also deregulated expression of numerous inhibitory immune checkpoint molecules including TIGIT, LAG3 and PD-1 which were more highly expressed in d-MMR compared to p-MMR tumors." (PMID 36781556, 2023). "However, the relationship between CD155 and TIGIT in colorectal cancer (CRC) prognosis is not known." (PMID 35324958, 2022). "Interestingly, TIGIT was also expressed on cancer cells of colorectal cancer, but this expression pattern did not affect cell proliferation in vitro." (PMID 35433470, 2022). "Similarly, we observed an increased frequency of TIGIT+ cells in both CD4 and CD8 TILs when compared with T cells in peripheral blood from lung, cervical, gastric, and colorectal cancer patients; breast and esophageal cancer patients showed a similar trend, but it was not statistically significant." (PMID 31709176, 2019).
colorectal cancer (continued). "Furthermore, the relationship between SIGLEC15,TIGIT,LAG3,CTLA4, PDCD1LG2 immune checkpoints and Mapk14 was only verified by correlation analysis, and we need to further explore the mechanism of Mapk14 expression in colorectal cancer in vitro and vivo experiments, such as single cell RNA sequencing." (PMID 35141222, 2022). "Indeed, TIGIT is highly expressed on CD8 T cells co-expressing PD-1 infiltrating non-small cell lung carcinoma (NSCLC) and colorectal carcinoma (CRC) as well as several mouse tumor models." (PMID 26347741, 2015).